KL (klotho)
Diseases named in the same sentence as KL in open-access papers (continued):
Sharing a sentence is not in itself a finding about the gene and the disease.
Abdominal obesity (13 papers, 2016 to 2025). Excessive fat around the stomach and abdomen. "The review also demonstrated that s-klotho levels are inversely associated with specific components of MS, such as abdominal obesity and elevated TG levels, while a positive association was observed with elevated glucose levels." (PMID 40076542, 2025). "This cross-sectional study demonstrates that general and abdominal obesity in middle-aged and older women were significantly associated with low serum klotho levels." (PMID 36061981, 2022). "The concentration of Soluble Klotho protein was negatively associated with abdominal obesity and high triglyceride (TG) in the adjusted model (p < 0.05)." (PMID 35053218, 2022). "In conclusion, general and abdominal obesity were inversely associated with serum klotho levels in women." (PMID 36061981, 2022). "Multivariate models demonstrated that general and abdominal obesity in women was inversely associated with serum klotho levels." (PMID 36061981, 2022). "Central obesity was associated with increased Klotho levels [156.4 pg/ml vs 118.5 pg/ml, p = 0.0275] and FGF21 levels [93.0 pg/ml vs 70.1 pg/ml, p = 0.0193] as well as a decrease in FGF19 levels [160.6 pg/ml vs 229.4 pg/ml, p = 0.0264]." (PMID 32546231, 2020). "The role of Klotho in the female endocrine system could be an additional explanations of the observed sex-dimorphic association of Klotho in relation to central obesity in our study." (PMID 37522130, 2023). "The findings elucidate that individuals with higher WWI exhibit lower levels of serum Klotho, suggesting a potential link between central obesity and metabolic dysfunction." (PMID 40678338, 2025). "In this way, the present study showed that obese women presented reduced plasma and pulmonary levels of klotho despite increased central obesity." (PMID 39727499, 2024). "In the present study, an increase was observed not only in the pro-inflammatory cytokines, but there was also a reduction in anti-inflammatory cytokines such as klotho and IL-10 in the women presenting central obesity." (PMID 39727499, 2024). "Multiple studies linked FGF signaling and weight change, but studies relating Klotho and central obesity in childhood are scarce." (PMID 37522130, 2023). "Recent studies also demonstrated that serum klotho levels were negatively correlated with waist circumference in young women with polycystic ovary syndrome and among community-dwelling adults with abdominal obesity." (PMID 36061981, 2022). "In addition, the results of trend tests for quartiles of log10-transformed Klotho demonstrate that, when considering general obesity, central obesity, CKD, and NAFLD as outcome variables, the trend P-values are all less than 0.05." (PMID 40369033, 2025). "While no significant nonlinear relationships were observed between Klotho and CVD, general obesity, central obesity, and NAFLD, notable nonlinear associations were identified between Klotho and T2DM and CKD (P for non-linear < 0.05)." (PMID 40369033, 2025). "A recent large analysis of the NHANES also demonstrated significantly lower serum klotho levels among participants with abdominal obesity than those without." (PMID 36061981, 2022). "In general, significantly lower serum klotho levels were seen in adults aged 60 years and older, men, overweight and obese subjects, women with abdominal obesity, nonsmokers, alcohol users, and those with an eGFR <60 ml/min." (PMID 36061981, 2022).
cardiomyopathy (13 papers, 2016 to 2025). A disease of the heart muscle or myocardium proper. "Second, our previously published data showed that Klotho attenuated cardiomyopathy induced by high phosphate and global autophagy deficiency." (PMID 33915953, 2021). "In addition, the administration of Klotho-encoding transgenes improved cardiomyopathy in Klotho-deficient mice." (PMID 41141519, 2025). "Several recent studies have demonstrated that klotho deficiency is related to the development of cardiomyopathy and cardiovascular diseases, and a higher concentration of plasma klotho was an independent predictor of a lower likelihood of cardiovascular disease." (PMID 35453645, 2022). "Another study analyzed the association of serum FGF23 and Klotho in the progression of 287 patients with chronic heart failure (CHF) and cardiomyopathy (CMP) as the etiology." (PMID 39330350, 2024). "In murine cardiomyopathy, Klotho prevented the degradation of IκB (inhibitor of κB), preventing NF-κB p65 nuclear translocation." (PMID 39272986, 2024). "Low circulating Klotho levels in HF and high expression of Klotho in cardiomyopathy, however, are difficult to reconcile." (PMID 29849175, 2018). "The enhanced deficiency of Klotho in AKI patients superimposed with COPD will further lead to impaired endothelium-dependent vasodilation and impaired angiogenesis and is related to ischemic stroke and cardiomyopathy." (PMID 30149499, 2018). "Indeed, it was demonstrated that Klotho protein has a cardioprotective effect and may be potential therapeutic agent in the treatment of cardiomyopathy." (PMID 34603200, 2021). "Instead, we show for the first time Klotho mRNA and protein upregulation in human cardiomyopathy, independent of sKlotho levels in the serum suggesting paracrine local affects." (PMID 29849175, 2018). "Soluble Klotho protects against cardiomyopathy in CKD independent of FGF23 and phosphate." (PMID 36776982, 2023). "Furthermore, we examined the role of Klotho in human specimens of cardiomyopathy (CMP) and non-failing hearts." (PMID 29849175, 2018).
colorectal cancer (13 papers, 2013 to 2025). A primary or metastatic malignant neoplasm that affects the colon or rectum. "In view of these observations, we conducted this prospective study to analyze the promoter hypermethylation status of KLOTHO gene in colorectal cancer patients and elucidate its association with various clinic-pathological parameters." (PMID 27844013, 2015). "Also, two studies have showed that Klotho variants (rs1207568, rs564481 and G‐395A) are associated with colorectal cancer risk." (PMID 35841322, 2023). "Further, mutations in G‐395A AA and GA genotypes in the promoter region of Klotho gene down‐regulate tissue Klotho expression in colorectal cancer." (PMID 35841322, 2023). "The analyses of publicly available DNA methylation datasets revealed a specific site in the first exon of KLOTHO, within a CpG island, that is hypermethylated in human colorectal cancer." (PMID 32585905, 2020). "Hypermethylation of the first exon, as well as promoter hypermethylation, negatively regulated Klotho expression in colorectal cancer." (PMID 32585905, 2020). "In colorectal cancer models, Klotho overexpression has been shown to reduce overall β-catenin expression, inhibiting transcriptional pathway activity by binding to the Wnt3a ligand, and thereby decreasing nuclear translocation of β-catenin." (PMID 32585905, 2020). "It is shown that klotho can suppress tumor growth and improve survival in several human malignancies, including lung, pancreatic, breast and colorectal carcinoma." (PMID 32614356, 2020). "Our previous study also demonstrated that KL functioned as a tumor suppressor in colorectal cancer by inhibiting the IGF1R-mediated PI3K/AKT pathway." (PMID 29884183, 2018). "Klotho (KL) was originally characterized as an aging suppressor gene, and has been identified as a tumor suppressor gene in a variety of cancers, including colorectal cancer." (PMID 29884183, 2018). "We analyzed the promoter hypermethylation of KLOTHO gene in 50 histopathologically confirmed tumor and adjacent normal tissues of colorectal cancer patients." (PMID 27844013, 2015). "We conclude that this novel tumor suppressor gene is epigenetically inactivated in colorectal cancer in our population paving way towards the potential of KLOTHO promoter hypermethylation as a predictor of the prognosis in colorectal cancer patients." (PMID 27844013, 2015). "We assessed promoter hypermethylation of KLOTHO in 50 colorectal carcinoma tissues and in adjacent normal tissues as controls." (PMID 27844013, 2015). "Recently the relevance of KLOTHO promoter hypermethylation in colorectal carcinoma in humans has been reported." (PMID 27844013, 2015). "Finally, in colorectal cancer, Klotho suppresses the tumorigenic effects of senescent stromal cells by suppressing SASP factors and CCL2." (PMID 40004457, 2025). "Thus KLOTHO promoter hypermethylation can be used as an independent prognosis factor to predict the outcome of colorectal carcinoma patients, however larger study patients and follow up study is needed to substantiate the results of this study." (PMID 27844013, 2015). "Methylation in promoter region of KLOTHO was analyzed by MS-PCR in colorectal carcinoma patients." (PMID 27844013, 2015). "The investigators tested the effects of Klotho in vivo on either chemically induced carcinogenic, or orthotopic mouse models in which MC38 colorectal cancer cells were injected into the colonic submucosa." (PMID 32585905, 2020). "Also, in human colorectal cancer (CRC) specimens, KL promoter methylation with reduced KL mRNA is frequent." (PMID 33520985, 2020). "Not only was XBP1 found to be elevated in response to Klotho, exposure to a UPR inhibitor, tauroursedeoxycholic acid (TUDCA), partially rescued the effect of Klotho on colorectal cancer cell colony formation, supporting the ability of Klotho to modulate UPR pathways." (PMID 32585905, 2020).
colorectal cancer (continued). "The study elucidates an intricate role of KLOTHO promoter hypermethylation in colorectal carcinoma irrespective of any discernible role in clinical and histo-pathological parameters." (PMID 27844013, 2015).
injury (13 papers, 2013 to 2025). Damage inflicted on the body as the direct or indirect result of an external force, with or without disruption of structural continuity. "Nevertheless, the conclusion that serum Klotho may be useful for early discrimination between the patients at low risk of developing severe kidney injury after surgery and the patients at high risk (AKI stage 2) is supported by the results of both studies." (PMID 33033444, 2020). "Using the decision trees models, serum Klotho may be useful to identify patients at low risk of developing more severe kidney injury after cardiac surgery using CPB and separate them from patients at high risk already in the first hours after surgery." (PMID 33033444, 2020). "Consistent with the current findings, Zhang showed that Klotho levels can be affected by PPARγ activation in a mouse model of traumatic brain injury." (PMID 36556233, 2022). "Based on recent research, Klotho protein is recognized as having a renoprotective effect and is used as a biomarker of kidney injury." (PMID 36555091, 2022). "In favour of a rationale that supports the protective role of Klotho, we decided to examine Klotho as a potential preventive/therapeutic agent in I/R heart injury." (PMID 32319182, 2020). "By contrast, in vivo Klotho gene delivery ameliorates renal damage and improves renal function in experimental models of kidney injury." (PMID 24386260, 2013).
fibrosis (12 papers, 2013 to 2026). the formation of excess fibrous connective tissue in an organ or tissue in a reparative or reactive process. "Growth retardation, vascular aging, renal disease, heart disease, lung disease, multiorgan fibrosis, bone loss, cognitive disorder, and life shortening are exhibited by klotho-deficient mice." (PMID 39507897, 2024). "Histopathological staining and creatinine and urea levels suggest that BSA treatment of Klotho-deficient mice by intraperitoneal gavage causes glomerular fibrosis and mesangial proliferation." (PMID 33767585, 2021). "We studied the associations of calcium, phosphate, 25D, PTH, FGF23, Klotho and T50 with histological fibrosis." (PMID 28036331, 2016). "In the current study, we provide evidence that Klotho alleviates renal tubulointerstitial fibrosis and renal tubular EMT in HFD- and STZ-induced DM mice." (PMID 32054986, 2020). "Estimated glomerular filtration rate correlated inversely with renal and PBMC levels of KL promoter methylation (r=-0.829, P<0.001; r=-0.645, P<0.001), while tubulointerstistial fibrosis score correlated positively (ρ=0.826, P<0.001; ρ=0.755, P<0.001)." (PMID 24224012, 2013). "CRS mice showed a significant increase of circulatory and renal FGF23 protein levels, as well as an upregulation of p-GSK, active-β-catenin, TGF-β, collagen I and vimentin, a downregulation of renal Klotho expression and induction of cardiorenal dysfunction and cardiorenal fibrosis." (PMID 33460402, 2021). "A deficit in klotho concentration may explain some of the clinical manifestation observed in SSc, such as digital ulcers, calcinosis, or fibrosis." (PMID 28912623, 2017). "Our data demonstrate that the presence of Klotho proteins in UDSCs downregulated both the canonical and non-canonical pathways in the HK-2 fibrosis model." (PMID 35563402, 2022). "However, the precise molecular mechanisms by which Klotho regulates EMT and tubulointerstitial fibrosis during the progression of DKD are largely unknown." (PMID 32054986, 2020).
Hypercalcemia (12 papers, 2012 to 2025). An abnormally increased calcium concentration in the blood. "An affected 13-year-old girl with a homozygous loss of function KLOTHO mutation presented severe tumoral calcinosis, carotid artery calcifications, hypercalcemia, and high renal tubular reabsorption of phosphate as observed in the GMC Klotho KO mice." (PMID 37160609, 2023). "In particular, mild hypercalcaemia, which had been reported to arise in association with increased renal synthesis of 1,25 dihydroxyvitamin D in klotho deficient mice, or from hyperparathyroidism as occurred in the KL mutation patient, was absent in kl203X/203X mice." (PMID 25860694, 2015). "Global Klotho KO mice challenged with a diet low in Ca2+, PO34−, and vitamin D show hypercalcemia, renal Ca2+ wasting, osteopenia, and intestinal Ca2+ hyperabsorption, highlighting that the Ca2+ leak is likely a consequence of Klotho failing to anchor TRPV5 to the membrane." (PMID 40165603, 2025). "Neither decreased Klotho protein nor hypercalcemia was observed in the lung or epithelial cells of CD9/CD81 DKO mice; therefore, it is unlikely that the Klotho protein actively participates in the pathogenesis of DKO mice." (PMID 29572511, 2018).
hyperparathyroidism (12 papers, 2013 to 2025). Hyperfunction of the parathyroid glands resulting in the overproduction of parathyroid hormone. "Although FGF23 can directly block PTH synthesis and secretion from the parathyroid gland primary cells via both the Klotho/FGFRs pathway and the Klotho-independent pathway, it can also indirectly induce hyperparathyroidism." (PMID 35269640, 2022). "High levels of Klotho could result in hyperparathyroidism and hypophosphatemic rickets, or have other toxic effects." (PMID 32982966, 2020). "Yet, it is conceivable that parathyroid Klotho has a functional impact on vitamin D metabolism in PTH-KL−/− mice and that their elevated 1,25(OH)2D level contributes to normalizing PTH and counteracts development of hyperparathyroidism." (PMID 24348262, 2013). "High serum levels of calcium may follow from hyperparathyroidism or high serum vitamin D levels which may then suppress production of another hormonal regulator, FGF23, and lead to down-regulation of klotho, a cancer prevention protein." (PMID 23866097, 2013).
Infertility (12 papers, 2010 to 2024). "Klotho-deficient mice showed numerous phenotypes consistent with premature aging, including kyphosis, slow movement, infertility, severe skeletal muscle reduction, and osteopenia, as well as atrophy of the skin, intestines, thymus, spleen and kidneys." (PMID 30222592, 2018). "Next, we investigated whether the selected candidates, GSTP1, GSTO2, and GSTK1, played important roles in the observed infertility caused by decreased Klotho expression." (PMID 37759974, 2023). "Although mice with Klotho deficiency are infertile, and an association between serum Klotho levels and human infertility has been reported, the etiology remains unclear." (PMID 37759974, 2023). "An association between lower Klotho levels and poor sperm quality in patients with infertility has been reported, although the etiology remains unclear." (PMID 37759974, 2023). "Men with infertility and lower sperm counts have lower serum Klotho levels than those in men with higher sperm numbers." (PMID 37759974, 2023). "Although previous studies have demonstrated that the loss of Klotho in mice causes infertility, its pathogenesis has not been fully explored." (PMID 37759974, 2023). "In humans, Klotho levels positively correlate with sperm quality in men with infertility." (PMID 37759974, 2023). "Male mice lacking Klotho are sterile, and decreased Klotho levels in the serum are observed in men suffering from infertility with lower sperm counts." (PMID 37759974, 2023).